RNU6-877P (RNA, U6 small nuclear 877, pseudogene)
Gene: Small nuclear RNA gene on chromosome 1 (51,382,308 to 51,382,414, forward strand). Ensembl gene ENSG00000206595.
Homologues: Orthologues: chimpanzee U6 (97% identical), macaque U6 (90% identical), guinea pig U6 (82% identical), rabbit U6 (76% identical). Paralogues in human: RNU6-166P (90% identical), RNU6-1060P (89% identical), RNU6-41P (89% identical), RNU6-748P (89% identical), RNU6-15P (88% identical), RNU6-393P (88% identical), RNU6-47P (88% identical), RNU6-536P (88% identical), RNU6-949P (88% identical), RNU6-1081P (87% identical), RNU6-10P (87% identical), RNU6-1152P (87% identical), and 1287 more.